NUP98 (nucleoporin 98 and 96 precursor)
Diseases named in the same sentence as NUP98 in open-access papers (continued):
Sharing a sentence is not in itself a finding about the gene and the disease.
cancer (25 papers, 2014 to 2025). A tumor composed of atypical neoplastic, often pleomorphic cells that invade other tissues. "Mutations of NUP98 have been so far investigated in cancer, mainly hematological malignancies, with the major focus on the expression of the NUP98 chimeric allele." (PMID 36835439, 2023). "Nup98 and Nup96 are also mutated in a number of other cancers, suggesting that their disruption is not limited to blood cancers." (PMID 35107131, 2022). "The significant downregulation of Lnp1, a fusion partner of NUP98 associated with hematopoietic malignancies, underscores the potential cancer-related implications of FAE, aligning with results from other studies that have linked folate metabolism to increased cancer risk." (PMID 41509541, 2025). "We suggest that the loss of normal Nup98 and Nup96 function may de-regulate the cell cycle to cooperate with other mutations in cancer." (PMID 35107131, 2022). "NUP98 has an established role in cancer as a fusion partner associated with leukaemogeneis." (PMID 30935371, 2019). "This may help to explain contexts of Nup98 and/or Nup96 loss that could predispose for cancer." (PMID 35107131, 2022). "Human NUP98-96 (also known as NUP98) is located near a known imprinted tumor-suppressor region in the genome, which could be significant as loss of heterozygosity via mutation or epigenetic modifications for the remaining NUP98-96 locus may occur in cancers exhibiting translocations." (PMID 35107131, 2022). "Although the oncogenic properties of NUP98 fusion proteins in hematologic malignancies are well characterized, NUP98 plays an opposite role in other cancers." (PMID 39080077, 2024). "Most of the attention on Nup98 translocations in cancer has focused on overexpressing Nup98 fusion partners." (PMID 35107131, 2022). "The first link between NUP98 and cancer came from its identification as a fusion partner with HOXA9 in AML patients." (PMID 30935371, 2019). "The clinical overlap of NUP98-mutated and RTS2/RTS1 patients, accounted by converging dysregulated gene networks, supports this first-described constitutional NUP98 disorder, expanding the well-known role of NUP98 in cancer." (PMID 36835439, 2023). "The NUP98-related disorder adds to the list of rapidly expanding nucleoporopathies, confirming NUP98 as an integral player in mitotic events and gene expression regulation, and its alterations are responsible for constitutional diseases besides cancer." (PMID 36835439, 2023). "HOX genes act as a fusion partner of nucleoporin 98 kDa (NUP98) to drive cancer progression." (PMID 34617205, 2022). "Recent studies also revealed that fusions between IDR-rich NUP98 and TFs or epigenetic modifiers (such as driver genes in pediatric leukemias—homeobox protein Hox-A9 and lysine-specific demethylase 5A), induced aberrant transcriptional activity by phase separation, leading to cancer." (PMID 36905356, 2023). "Although most of the attention on Nup98 translocations in cancer has focused on overexpressing the fusion partners, there is increasing evidence that the disruption of endogenous Nup98 and/or Nup96 may contribute to enhanced proliferation that could cooperate with other oncogenic mutations." (PMID 35107131, 2022). "Similar to NUP98, NUP88 is overexpressed in a variety of human cancers, and, in this state, it sequesters the NUP98-RAE1 complex in the cytoplasm away from APC/CDH1, disturbing mitotic checkpoint control and promoting aneuploidy." (PMID 36835439, 2023). "NUP98 was expressed on the DCIS component of these cases, suggesting that this is an early event in cancer." (PMID 30935371, 2019).
cancer (continued). "NRG1 is a direct transcriptional target gene of NUP98 and functions along with its receptor ERBB4 in various normal and pathological conditions including cardiac development, cancer and neurodegeneration diseases, etc.." (PMID 31396490, 2019). "In conclusion, HOX genes are frequently engaged in NUP98 fusion, thus mediating cancer progression, by acting as fusion partner genes of NUP98, such as HOXA9 and HOXD13, or by mediating the effect of other NUP98 fusions as their target genes in a wide range of hematologic malignancies." (PMID 31013831, 2019). "We propose that disruption of the NUP98-96 locus in cancers with or without NUP98 translocations may contribute to tumorigenesis through aberrant JNK signaling and AIP, in the presence of additional hits that block cell death." (PMID 35107131, 2022). "Interestingly, our panel included genes already described to be cancer predisposition genes (FAS, ITK, KIF1B, PGR and MET) or previously reported as playing important roles in cancer (ABI1, ARID5B, DNMT3A, HEY1, KDM5C, NCOA1, NUP98, and SLC34A2), or in DNA repair process (FANCF)." (PMID 30925779, 2019).
infection (22 papers, 2013 to 2025). The state of being infected such as from the introduction of a foreign agent such as serum, vaccine, antigenic substance or organism. "Bone marrow stem cells from these animals were immortalized by infection with virus encoding constitutively expressed HoxA9 or Nup98-HoxA9, in the continuous presence of IL-3 and GM-CSF." (PMID 24177192, 2013). "In concordance with our previous results, we found that NUP98 KD blocked BKPyV-GFP infection, but MCPyV-GFP was still only partially inhibited." (PMID 40445976, 2025). "Four hours after infection, nucleocytoplasmic trafficking disruption was already evident, as shown by the hyperphosphorylation of NUP98 (shift in migration), and numerous nuclear proteins were already enriched in the vicinity of PKR." (PMID 41406153, 2025). "Curiously, of the three nucleoporins targeted by 2Apro, NUP98 is cleaved most rapidly, with significant activity observed within 30 min of infection, whereas NUP62 and NUP153 are targeted later during active viral replication." (PMID 41101500, 2025). "Crucially, NS1 expression also reduces RAE1•NUP98 complex levels during infection, a biologically significant effect, as RAE1+/− or NUP98+/− cells show increased sensitivity to IAV infection." (PMID 41101500, 2025). "For EMCV, as this virus replicates much faster than TMEV, NUP98 was immunoprecipitated after 3h30 of infection." (PMID 36508477, 2022). "Analyzing the time of infection in which Nups degradation occurred, we found that Nup98 is the first NUP cleaved (from 12 h for ZIKV and at 24 h for DENV)." (PMID 32466480, 2020). "Reductions in NUP358 or NUP98 led to a visible reduction of HIV-1WT infection in HeLa-Ctrl cells (blank columns)." (PMID 32600399, 2020). "By contrast, infection with HIV-1N74D was minimally affected by NUP358 or NUP98 depletion both in HeLa-Ctrl and HeLa-MxB cells." (PMID 32600399, 2020). "In fact, two recent studies have demonstrated that NUP98 protein is indeed present in stress granules produced during cellular stress conditions induced by non-infection conditions." (PMID 31396490, 2019). "The results showed that Nup98, Nrg1, and erbB4 were upregulated during the acute phase of infection (7 dpi) and decreased at the chronic phase of infection (40 dpi) even though the extent of decrease for Nup98 expression was small." (PMID 31396490, 2019). "Targeted siRNA knockdown of NUP98 during infection further increased viral protein expression and viral titer, and reduced cell viability, suggesting a potential antiviral role of NUP98." (PMID 31396490, 2019). "Levels of the nuclear protein NUP98 were similarly maintained at 3 and 6 hpi after infection with both ΔpqsA and PAO1." (PMID 30619119, 2018). "Thus, we tested if depletion of either Rae1 or Nup98 altered hSpt16SUMO levels in mock-infected cells or inhibited hSpt16SUMO depletion during VSV-eGFP infection." (PMID 40060670, 2025). "We further investigated the significance of infection-mediated downregulation of NUP98." (PMID 38449868, 2024). "Moreover, silencing of NUP358 and NUP98 each abolished or reduced the magnitude of MxB inhibition of HIV-1WT infection." (PMID 32600399, 2020). "However, a significant reduction (p= < 0.05) in the amount of Nup98 was observed after the transfection with the active form of the viral protease as well as during infection." (PMID 32466480, 2020). "In addition, expression of these NUP98 target genes in myocardium tissue not only occurred at an earlier phase of infection, but also appeared in areas away from the initial inflammatory regions." (PMID 31396490, 2019). "Further, knockdown of NUP98 resulted in dramatic reduction of its transcriptional targets leading to impaired cardioprotection, increased viral titer and decreased cell viability during infection." (PMID 31396490, 2019). "Moreover, we found that cleavage of NUP98 leads to the downregulation of cardioprotective genes Nrg1 and erbB4 in later phase of infection." (PMID 31396490, 2019).
infection (continued). "In addition, the influenza A virus down-regulates Nup98 to facilitate its infection." (PMID 36051755, 2022). "Cleavage products of Nup98 were detected in CVB3 and CVB3–2Awt infected cells from 2 hours post infection (hpi) onwards, with complete cleavage at 6 hpi." (PMID 40875754, 2025). "Since NUP98 was the only NUP that was downregulated at the protein levels during both transfection in HEK293T and infections in SupT1 and HEK293T cells, we continued our investigations on NUP98." (PMID 38449868, 2024). "Alterations in nucleoporin distribution are also observed during infection with DENV2 and HCV, where Nup98 is relocated to the cytoplasm." (PMID 32466480, 2020). "The integrity and abundance of Nup98 during DENV2 and DENV4 were analyzed by confocal microscopy at 48 hrs post-infection." (PMID 32466480, 2020). "We observed that NUP98 protein levels were decreased both in SupT1 and HEK293T cell types upon HIV-1 NL4.3 infection by 4.7- and 1.5-fold, respectively (respectively), whereas the protein levels of other NUPs such as NUP62, NUP155, NUP133, NUP107, and NUP85 remained unaffected." (PMID 38449868, 2024). "Notably, 9 nucleoporins (NUP58, NUP214, NUP98, NUP54, NUP62, NUP88, NUP153, POM121/NUP121 and RANBP2/NUP358) and the mRNA export factor Rae1 were present in both the CebN infection and transfection interactomes." (PMID 38712050, 2024). "Unlike many other NSs interactors, Nup98 is not consumed or dislocated over the course of infection." (PMID 31671053, 2020). "In addition, poliovirus 2A protease can target NUP98, NUP62 and NUP153 for cleavage during the course of infection, resulting in the cellular relocalization of NUPs." (PMID 31396490, 2019). "The CsA dependence of HIV-1A92E infection in HeLa cells was exaggerated by some Nup knockdowns (e.g. NUP93, NUP205, NUP54, NUP153) while other knockdowns reduced or eliminated the enhancing effects of CsA (e.g. NUP98, NUP107, NUP155)." (PMID 30084827, 2018). "Notably, reductions in NUP358 or NUP98 did not reduce HIV-1WT infection to a significantly lower level in HeLa-MxB cells (black columns)." (PMID 32600399, 2020). "In addition, Nup98 levels did not change in rZH-CFNSs infection when compared to a control virus expressing a Flag-tagged fragment of MxA (rZH-FΔMx) instead of NSs, as shown by immunoblot analyses." (PMID 31671053, 2020). "In contrast, and inconsistent with the results obtained by Western analysis, staining for Nup98 revealed no marked change over the course of infection, which could be a consequence of the antibody epitope remaining preserved and in situ despite cleavage." (PMID 23951130, 2013). "Additionally, Nup98, Nrg1, and erbB4 were all upregulated in the murine myocardium during acute/early phase of CVB3 infection, and Nrg-1 and erbB4 were downregulated at a later phase of infection, suggesting a cardioprotective role of this signal cascade in cellular response to infection." (PMID 31396490, 2019). "However, unlike VSV-M or ORF6, the RAE1•NUP98•ORF10 complex retains RNA-binding capacity, indicating that ORF10 overrides RAE1’s native specificity and contributes its own RNA-binding selectivity to support the export of transcripts promoting infection." (PMID 41101500, 2025).
hematological malignancies (18 papers, 2013 to 2025). "All these data seem critical for the optimal management of NUP98‐LEDGF + hematological malignancies commonly associated with a poor prognosis." (PMID 30848074, 2019). "Nucleoporin 98 fusion–driven (NUP98 fusion–driven) leukemia represents a distinct and challenging category of hematological malignancies." (PMID 40166939, 2025). "Over 30 NUP98 fusion oncoproteins were described in a spectrum of hematologic malignancies with poor prognosis." (PMID 34680332, 2021). "Overall, despite heterogeneous clinical and biological features, NUP98‐LEDGF+ hematological malignancies usually present as very aggressive disorders." (PMID 30848074, 2019). "NUP98 fusion proteins form phase-separated condensates and promote transcriptionally active chromatin loops at proto-oncogenic locus, further assembling super-enhancers to amplify oncogene activation in human hematological malignancies." (PMID 40507965, 2025). "Previous studies have summarized the role of NUP98 fusion in hematologic malignancies." (PMID 39080077, 2024). "NUP98::HOXA9 was the first described NUP98 fusion in hematological malignancies." (PMID 39323480, 2024). "NUP98 is a gene known to fuse with different partner genes in several hematological malignancies." (PMID 35494081, 2022). "Nucleoporin 98KD (Nup98) is a promiscuous translocation partner in hematological malignancies." (PMID 35107131, 2022). "Deletion of ABL1 was detected in a cohort of hematologic malignancies carrying AML1-ETO and NUP98 fusion proteins." (PMID 36959186, 2023). "NUP98, NUP160, and NUP214 have both been reported as fusion proteins with a variety of partners that lead to hematologic malignancies and angiosarcoma." (PMID 31867128, 2018). "This early work identified fusions of NUP98 and NUP214 that led to a variety of de novo hematologic malignancies." (PMID 31867128, 2018). "NUP98 (Nucleoporin 98 gene) is reportedly fused to various partner genes, including some homeobox (HOX) genes, in hematological malignancies, (mostly AMLs) with 11p15 translocations." (PMID 23936658, 2013). "These comprise master transcription factors of the leukemogenic program of NUP98::KDM5A-driven AML, as well as other genes which have not been associated with hematologic malignancies." (PMID 40389480, 2025).
tumor (15 papers, 2011 to 2026). "In AML, the FLT3 mutation was significantly associated with NUP98 fusions and indicated a higher tumor burden." (PMID 39273530, 2024). "We found that NUP98 is connected to the regulation of genes implicated in neoplasm formation especially at the progenitor stage." (PMID 23468646, 2013). "We simultaneously inhibited Nup98 and Nup96 in Drosophila using an in vivo RNAi knockdown approach and observed cell cycle de-regulation and cooperation with oncogenic mutations, consistent with a tumor-suppressor function for Nup98 and/or Nup96." (PMID 35107131, 2022). "In NUP98-rearranged neoplasia, the 5′-NUP98::partner-3′ genomic fusion must typically be transcribed and translated to an oncoprotein to unfold its leukemogenic potential." (PMID 37296904, 2023). "Our data suggest that this locus can behave as a dominant negative when the Nup98 portion is overexpressed through translocations as well as a haplo-insufficient tumor suppressor in some contexts." (PMID 35107131, 2022). "Additional rare fusions like GATA2–HOXA9, MN1–FLI1, NIPBL–HOXB9, or NUP98–BPTF were cloned from tumor cells from pediatric AMKL patients." (PMID 31681706, 2019). "Furthermore, gene NUP98, classified as dominant mutation in the COSMIC database but located at a tumor suppressor gene region, is also included in this set of 48 genes." (PMID 21429208, 2011). "Earlier findings indicated that NUP98 may also have a role as a tumor suppressor." (PMID 39000572, 2024). "Specifically, it reversed enhancement in tumor growth, mass, and expression of downstream genes (NUP62, NUP93, and NUP98), accompanied by modulation of NPC numbers and Ki-67 or CD31 labeling index." (PMID 41510169, 2026). "The mechanistic basis involves ARMC12, which functions within liquid-liquid phase-separated condensates to co-activate MYC, driving the subsequent up-regulation of NUP62, NUP93, and NUP98, elevation of NPC number, and tumor progression." (PMID 41510169, 2026). "The SENP1 expression level positively correlated with the expression levels of UBN1, SP3, SAP130, NUP98, NUP153 in 32 tumor types." (PMID 34276383, 2021).
blood cancers (3 papers, 2022 to 2026). "NUP98 rearrangements occur in various hematological neoplasms, especially in children with AML and T-ALL." (PMID 41419605, 2026). "This is the first report of NUP98::LEDGF positive malignant hematological tumor expressing T cell and myeloid lineage antigens." (PMID 39301554, 2024).
neurodegenerative disease (3 papers, 2024). A disorder of the central nervous system characterized by gradual and progressive loss of neural tissue and neurologic function. "Other neurodegenerative disease models have documented abnormalities in Nup98 such as reduced expression, cytoplasmic mislocalization, and possible nuclear membrane invaginations, all of which were observed at a higher proportion in cells treated with siA1." (PMID 39452051, 2024). "Further, aberrant Nup98 cytoplasmic localization and aggregates are observed in neurodegenerative diseases such as ALS, ALS/FTD, and AD." (PMID 38918634, 2024).
neurologic diseases (1 paper, 2024). "First, we examined markers for different compartments of the NPC which have been shown to been altered in neurologic diseases, including Nup62 and Nup98 in the central channel, POM121 to demarcate the transmembrane ring, and RanBP2 within the cytoplasmic ring and filaments." (PMID 39452051, 2024).
NUP98 also shares sentences with these, for which no sentence is quoted: lung carcinoma (4 papers); Autoimmunity (2); COVID-19 (2); blast crisis (1); chronic myelomonocytic leukemia (1); congenital heart disease (1); cyst (1); Down syndrome (1); juvenile myelomonocytic leukemia (1); lymphoid neoplasm (1); melanoma (1); multiple myeloma (1); myeloproliferative neoplasm (1); renal angiomyolipoma (1); Thrombocytosis (1); thyroid tumor (1).